IL13 (interleukin 13)
Diseases named in the same sentence as IL13 in open-access papers (continued):
Sharing a sentence is not in itself a finding about the gene and the disease.
asthma (continued). "Resolvin E1 also limited lymphocyte recruitment, IL-13 release, and airway hyper-responsiveness in a murine model of asthma." (PMID 23663457, 2013). "A considerable weight of evidence supporting a role for IL-13 in asthma was derived from animal models." (PMID 23437086, 2013). "Taken together, these results suggested that IL-13 was a critical cytokine in the development of asthma." (PMID 23437086, 2013). "We selected lung macrophages since they exhibit an M2 phenotype similarly to testicular macrophages, and the lung is the organ harboring the allergic inflammation in human pathologies such as asthma, mediated by IL-4 and IL-13." (PMID 24358127, 2013). "In mild asthma, Tbet expression was significantly correlated with Il2, Il4, Il5, Il6, Il13, and Tnfα expression." (PMID 23781124, 2013). "Overexpressing the IL-18 protein in the lungs induces type 1 and type 2 cytokines and airway inflammation, and results in increasing airway hyperresponsiveness via CD4+ T cells and IL-13 in asthma." (PMID 23382928, 2013). "Subepithelial/peribronchial fibrosis is characterized by extracellular matrix protein deposits beneath the basal lamina, which is controlled by the cytokines such as IL-4 and IL-13 in asthma." (PMID 24040386, 2013). "It was demonstrated that similar to human asthma, this experimental disease is mediated by IL-4 and IL-13 cytokines." (PMID 24358127, 2013). "Since IL-4 and IL-13 share receptor complexes, however, the exact contribution of the individual receptor complexes in inducing asthma pathophysiology is unclear." (PMID 23940740, 2013). "Recently, several biological agents, including anti-immunoglobulin E (IgE) monoclonal Ab (mAb), anti-IL-13 mAb and anti-IL-5 mAb, have been developed for difficult-to-treat or severe asthma." (PMID 23855490, 2013). "Howard and coworkers showed that two of the SNPs (−1111C>T and 4257G>A) in the human IL-13 gene have the strongest relationship with the incidence of asthma in the Dutch population." (PMID 23865080, 2013). "However, the role of IL-13 +1923C/T polymorphism (rs1295686) on risk of asthma was still unknown." (PMID 23841068, 2013). "Th2 lymphocytes play an important role in the initiation and progression of allergic diseases, including asthma, by releasing IL-4, IL-5, and IL-13." (PMID 23843865, 2013). "STAT6 expression in lung epithelial cells is exclusively required for IL-13-mediated pathology, consistent with the increasing recognition that epithelial cells play a fundamental role in asthma pathogenesis." (PMID 23402658, 2013). "Sprr2 transcription can be also regulated by IL4/IL13/Stat6, as described in an experimental asthma mouse model." (PMID 23844115, 2013). "The ability of siRNA treatment to attenuate IL-13-induced CCL26 in primary NEC's from asthma patients further supports the therapeutic potential of this approach." (PMID 23402658, 2013). "Experimental asthma models indicate that these cytokines, IL-13 in particular, are critical in driving key pathologic features of the allergic response." (PMID 24032029, 2013). "In a recently published trial, the monoclonal antibody (mAb) to IL-13, lebrikizumab, when administered to patients with chronic moderate-to-severe asthma for 12 weeks, significantly increased baseline spirometry (5.5%)." (PMID 24032029, 2013). "The Th2 cytokines IL-4 and IL-13 promote acute inflammatory processes in the pathogenesis of asthma and structural changes in the airways;." (PMID 23451048, 2013). "In animal models, just as in cases of patients with asthma, IL-17 induces pathology by enhancing neutrophil influx, mucus and IL-13 production." (PMID 23462708, 2013). "IL-13, independent from IL-4, plays a central role for the development of asthma-related symptoms in animal models and human studies." (PMID 23382814, 2013). "In Th2 cell-driven murine asthma models, mucus production and eosinophilia depend on IL-13 and IL-5." (PMID 23976880, 2013).
asthma (continued). "Our study also discovered that the serum levels of IL-4, IL-17 and IL-13 in the asthma group were significantly higher than those in the alleviated group and control groups." (PMID 23717481, 2013). "It should be noted, that seminal studies showing a role for IL-13 in S. mansoni egg granulomatous fibrosis led to the evaluation of IL-13 as a therapeutic target in other fibrotic conditions such as asthma." (PMID 23596444, 2013). "IL2, IL4, IL5, IL6, IL13, and TNFαhave been reported to enhance asthma in humans, and Th1 cells have been shown to suppress Th2 cells through the release of IFN-γ." (PMID 23781124, 2013). "Most anticytokine strategies under current development for the treatment of asthma mainly target Th2-derived cytokines, including IL-5, IL-4, and IL-13, crucially involved in the pathobiology of allergic phenotypes." (PMID 23853765, 2013). "Our previous publications have shown that maternal smoking during pregnancy interacts with the IL13 and IL1RN genes and increases the risk of asthma and wheezing." (PMID 24004509, 2013). "This study showed significantly higher IL-13 production in asthmatic patients compared to control subjects, and this supports the idea that IL-13 plays an important role in the pathogenesis of asthma." (PMID 23865080, 2013). "Further work is required to quantify the secretion of other cytokines, chemokines and growth factors by neonatal nasal AEC stimulated with a range of asthma-relevant cytokines such as IL-4 or IL-13." (PMID 24223790, 2013). "While both IL-4 and IL-13 can elicit asthma pathology when provided exogenously, it is evident that they mediate different responses in vivo." (PMID 23940740, 2013). "Up to the present, two studies concerning IL-13-environmental interaction on asthma phenotypes in children have been reported." (PMID 23382814, 2013). "Acute viral infection leads to the production of IL-13 which has been shown to be responsible for many characteristics of asthma." (PMID 23555047, 2013). "Recently, Saha and coworkers suggested that IL-13 overexpression in sputum and bronchial biopsy specimens was a feature of severe asthma." (PMID 23841068, 2013). "We have not measured DNA-M in airway tissue; however, the major source of IL-13 production in the airways is inflammatory cells, and methylation measurements in peripheral blood are likely to better reflect asthma-related immune mechanisms." (PMID 24314122, 2013). "Although Th2 molecules such as IL-4, IL-5, and IL-13 are key cytokines involved in the inflammatory response in asthma, IFN-γ has also been associated with asthma severity." (PMID 22934153, 2012). "Previous studies have found that excessive secretion of Th2 cytokines, including IL-4, IL-5, and IL-13, is able to aggravate pathological asthma symptoms." (PMID 23049614, 2012). "Upon stimulation with a purified HDM extract, PBMCs from asthma patients tended to have a higher IL-13 response (1632 pg/mL) than healthy controls (695 pg/mL p = 0.096), suggesting a Th2 skewed response in asthma patients." (PMID 23091602, 2012). "Th2 cytokines, especially IL-13, are central mediators of asthma, and IL-13 potently induces goblet cell metaplasia by human airway epithelial cells." (PMID 23244755, 2012). "As a result, clinical assessment of anti-IL-13 antibodies is being explored in the treatment of asthma with some improvement in lung function indicated." (PMID 22251275, 2012). "Further interactions involving the B cell surface marker, CD21, with soluble CD23 and B cell cytokine stimulation (IL-4, IL-13) induces the generation of plasma cells specific for the immunoglobulin IgE, the most common immunoglobulin in allergy and asthma." (PMID 22251275, 2012). "Methacholine hyporesponsiveness has previously been described in mice overexpressing Gαi, and the IL-13-knockout mouse asthma model." (PMID 23056391, 2012).
asthma (continued). "Stimulated PBMCs from asthma patients clearly showed higher IL-13 and IL-5 and lower IFNγ responses as compared to those of healthy controls." (PMID 23091602, 2012). "In OVA and house dust mite- (HDM-) induced experimental asthma, ILCs2 are the main source of IL-5 and IL-13 production." (PMID 23209480, 2012). "Th2-driven airway inflammation was identified in patients with comparable increased levels of corresponding cytokines (such as IL-4, IL-5, and IL-13) in induced sputum in both EB and asthma." (PMID 22839528, 2012). "We focused on IL-13-responsive genes given (a) our prior in vivo observations showing marked simvastatin inhibition of IL-13 production in mouse lung lavage fluid, and (b) its importance in human asthma and allergic inflammation." (PMID 22583375, 2012). "VCAM1 had previously been implicated as a key player in the inflammation process; therefore the microarray further validated the role of IL13 in asthma." (PMID 22500180, 2012). "Administration of rapamycin prior to the induction of asthma significantly inhibited lung mRNA levels of canonical Th2 (IL-4 and IL-13) and Th17 (IL17A) cytokines." (PMID 22685525, 2012). "In the search for an inflammatory mediator for asthma, IL-13 was found to play a critical role in murine asthma models." (PMID 22500180, 2012). "The cytokines, IL-4 and IL-13, are known to be up-regulated in allergy/asthma and have been characterized as integral proteins in GBM biology." (PMID 22251275, 2012). "A clearer picture of the role of IL-4 and IL-13 blockers in the treatment of severe asthma is likely to emerge over the next few years." (PMID 21896202, 2011). "Studies have shown that GABA-α receptors mediate the hypersecretion of glycoproteins into the mucus barrier, under the control of IL-13 in asthma models." (PMID 21155842, 2011). "CD4+ T helper type 2 (TH2) cytokines such as IL-4, IL-5 and IL-13 play a critical role in inducing allergy and asthma." (PMID 22014099, 2011). "Genes within the chromosome 5q cytokine cluster have demonstrated strong associations with asthma/allergy, most notably for IL4 and IL13." (PMID 21320344, 2011). "A number of clinical trials employing monoclonal antibodies targeting IL-4 and/or IL-13 in asthma are underway." (PMID 21896202, 2011). "IL-2, IL-4, and IL-13 have all been found to be up-regulated in patients with steroid-resistant asthma." (PMID 23283176, 2011). "For example, in a mouse model of asthma, IL-13 signaling results in mucin secretion, airway hyper-reactivity, fibrosis, and chitinase up-regulation." (PMID 23283176, 2011). "This study evaluated 8 of these genes (IL4, IL13, TNF-α, HLA-DRB1, HLA-DQB1, FCER1B/MS4A2, CD14, ADAM33) as well as 3 glutathione-s-transferase genes (GSTM1, GSTP1, and GSTT1) for association with asthma/allergy among urban-residing African Americans." (PMID 21320344, 2011). "Clinical trials are currently underway to investigate blockade of IL-13/IL-13 signaling in the treatment of asthma." (PMID 23283176, 2011). "A study in Germany reported that secondhand smoke exposure increased IL-13 levels in children with asthma." (PMID 22013915, 2011). "SERPINB3 has been shown to be upregulated in bronchial epithelial cells from asthma patients by Th2 cytokines IL-4 and IL-13." (PMID 21887273, 2011). "Inhibition of arginase I by RNA interference suppresses IL-13-mediated AHR in a murine model of asthma and inhalation of an arginase inhibitor decreases AHR and airway inflammation in a guinea pig model of asthma." (PMID 21867534, 2011). "While the list of cytokines potentially involved in asthma is long, both TNFα and IL-13 have been the focus of considerable investigation." (PMID 21858195, 2011). "Asthma is a reversible airway disease characterized by airway hyper-reactivity, inflammation and airway remodeling, and interleukin-13 (IL-13) is a recognized effector in these processes." (PMID 23283176, 2011).
asthma (continued). "Severity of asthma was associated with increased both serum IgE and frequencies of CD4+/IL-13+ T cells, as well as duration of disease." (PMID 21197090, 2010). "Asthma is a chronic inflammatory disease of the airways, driven by Th2 lymphocytes and the type II cytokines IL-4, IL-5 and IL-13." (PMID 21203444, 2010). "Th2 cytokines also activate secondary effector cells in asthma including the recruitment of mast cells (IL-4, IL-9 and IL-13) and basophils (IL-3 and IL-4), whilst IL-5 supports growth, differentiation, and activation of eosinophils." (PMID 19769993, 2010). "IL33 amplification of IL13-induced alternatively-activated macrophage polarization in asthma patients has also recently been suggested." (PMID 20625511, 2010). "The preponderance of IL-4 and IL-13 relative to the type 1 cytokine IFN-γ is believed to promote feed-forward mechanisms of allergic inflammation in asthma." (PMID 20667106, 2010). "In contrast, an increase in IL-13 in CD4+ T cells in severe asthma was revealed, though it was only significant as compared to intermittent asthma." (PMID 21197090, 2010). "In subjects with asthma, 29.8±3.5% and 36±3.5% of the IL-4+ and IL-13+ blood T cells expressed CCR8 while only 4.3±1.0% of IFN-γ+ cells expressed CCR8 (P<0.001)." (PMID 20455898, 2010). "In Alternaria-sensitive moderate-severe asthma, Alternaria extract stimulated lymphocytes had significantly increased synthesis of IL-5 and IL-13 compared to Alternaria-sensitive mild asthma (p = 0.008 and p = 0.004, respectively)." (PMID 20298583, 2010). "Goblet cell hyperplasia and collagen deposition, classical markers of IL-13 mediated remodeling in murine models of asthma, were strongly induced by sub-chronic allergic airway inflammation and were fully attenuated by anti-IL-13 antibody treatment." (PMID 20573261, 2010). "The percentage of CD4+/IL-13+ was significantly higher in severe asthma than in children with intermittent disease symptoms." (PMID 21197090, 2010). "A primary role for IL-13 in asthma and Th2-mediated fibrogenic reactions is the production of TGF-β1 via a STAT-6-dependent mechanism." (PMID 20738867, 2010). "The chronic HDM model of asthma has enabled us to investigate the effect of anti-IL-13 mAb treatment on both mechanism and disease-relevant endpoints." (PMID 20957211, 2010). "Because the fixed-effect model is more precise than random effect model, the strength of evidence of ADAM33 T1-C/T, ACE D/I, IL-13 -1923C/T, RANTES -28C/G, as risk factors for asthma was greater than that of FcεRIβ -6843G/A, IL-13 -2044A/G and TNF-α -308G/A." (PMID 20868478, 2010). "IL-13 dysregulation plays an important role in the pathogenesis of a variety of lung diseases including asthma, IPF, viral pneumonia, and COPD." (PMID 21067601, 2010). "As such, numerous approaches to blocking increased IL-13 in asthma are being evaluated, with emphasis on IL-13 neutralizing antibodies and soluble receptors, but the identification of oral, small molecule inhibitors of IL-13 would have obvious advantages." (PMID 20573261, 2010). "To further elucidate the role AR and potential clinical utility of its inhibitor fidarestat, we examined goblet cells metaplasia in exposed SAEC to IL-13, a Th2 cytokine and mouse model of asthma." (PMID 21203431, 2010). "IL-13 has been known to play a pivotal role in the pathogenesis of lung disease such as asthma, IPF, viral pneumonia and COPD." (PMID 21067601, 2010). "Our data demonstrating enhanced accumulation of not only IL-13+ but also IFN-γ+ T cells from asthmatic subjects in response to IL-2 suggest the importance of antigen-independent stimulation of T cells in asthma." (PMID 20667106, 2010). "A T-helper type 2(TH2) predominant inflammatory process initiated through the cytokines IL-4, IL-5, IL-9 and IL-13 is thought to be central to asthma pathophysiology." (PMID 20455898, 2010).
asthma (continued). "This study investigated the multiple-dose pharmacokinetics and safety profile of human anti-IL-13 antibody (CAT-354) in adults with asthma." (PMID 20064211, 2010). "In mild-moderate asthma, IL-6 dissociates from other proinflammatory biomarkers, but correlates with IL-13 levels." (PMID 20205953, 2010). "Increasingly, more evidence indicates that IL-13 plays a crucial role in the Th2 driven immunopathology and airway hyperresponsiveness seen in asthma." (PMID 21197090, 2010). "Further, blockade of IL-4 and IL-13 signaling locally in the airway provides significant protection in clinical studies of asthma." (PMID 20953328, 2010). "Frequencies of CD4+ T cells producing IL-10 as well as CD4+ T cells producing IL-13 was positively correlated with the duration of asthma (r = 0.44, P < .004 and r = 0.4, P < .01, resp)." (PMID 21197090, 2010). "Among them, seven polymorphisms (ADAM33 T1-C/T, ACE D/I, FcεRIβ -6843G/A, IL-13 -1923C/T, IL-13 -2044A/G, RANTES -28C/G and TNF-α -308G/A) were statistically associated with increased risk of asthma." (PMID 20868478, 2010). "By secreting a plethora of typical mediators such as interleukin (IL) 4, IL-5, and IL-13, these cells hold a key position in asthma pathogenesis." (PMID 20976014, 2010). "Our findings support the view that IL-13 expression is increased in peripheral blood-derived T cells in asthma and that asthmatic serum up-regulates IL-13 release from healthy peripheral blood mononuclear cells." (PMID 19602238, 2009). "Our findings further strengthen the argument for IL-13 being a key mediator in the pathogenesis of AHR in asthma." (PMID 19602238, 2009). "IL-13 is known to play critical role in airway hyperreactivity and amplifying allergic inflammation in asthma." (PMID 19781072, 2009). "A human anti human IL-13 IgG4 monoclonal antibody (CAT-354) that blocks IL-13 effects in an animal model of asthma is in phase II clinical trials in severe asthma." (PMID 18315837, 2008). "The 5q23.2-q34 region contains the cytokine gene cluster (IL4, Il13, IL5, IL12B) and has previously been suggested as an asthma/atopy susceptibility locus and the 7p21.1-14.1 region contains the previously identified asthma susceptibility gene, GPRA (7p14.3)." (PMID 18442398, 2008). "In two genome-wide screens, interactions between passive tobacco exposure and chromosome 5q, the region in which the IL-13 gene (IL13) is located, have been reported for asthma phenotypes." (PMID 18186920, 2008). "It has been suggested that tobacco smoke increases IL-13 and there are some reports on the combined effects of IL13 polymorphisms or other genetic variants in the IL13 region on asthma-related outcomes." (PMID 18186920, 2008). "It was observed that the T allele of -1111C > T had increased binding of a T cell transcription factor (NFAT), which regulates IL13 and IL4 expression and -1111TT homozygosity was associated with both asthma and altered regulation of IL13 production." (PMID 18197984, 2008). "This is the first report that shows a combined effect of in utero exposure to smoking and IL13 on asthma phenotypes in childhood." (PMID 18186920, 2008). "Interleukin-13 (IL-13) is an important cytokine involved in the IgE pathway and pathogenesis of asthma." (PMID 18186920, 2008). "Administration of the recombinant cytokine to mouse airways e.g. IL-13, has been shown to mimic several of the features of asthma including AHR." (PMID 17903241, 2007). "Mouse model of ovalbumin-induced bronchial asthma has shown that the acid mammalian chitinase (AMCase) is involved in the pathophysiology of asthma and acts downstream of interleukin-13." (PMID 19662198, 2007). "In a transgenic model of asthma induced by lung overexpression of IL-13, TGFβ1 mRNA and protein were observed mainly in macrophages, but also in type II pneumocytes, airway epithelial cells and occasionally in eosinophils." (PMID 17892594, 2007).